WDR55 (WD repeat domain 55)
Description:
Nucleolar protein that acts as a modulator of rRNA synthesis. Plays a central role during organogenesis (By similarity).
Synonyms: FLJ20195; FLJ21702
Tractability: Small molecule: a structure with a bound ligand is known. PROTAC: ubiquitination databases record sites on it; its protein half-life has been measured.
Gene: Protein-coding gene on chromosome 5 (140,664,868 to 140,674,124, forward strand). Ensembl gene ENSG00000120314.
Subcellular location: Nucleus, nucleolus; Cytoplasm
Subcellular location (Human Protein Atlas): Nucleoplasm; Nucleoli
Gene Ontology:
Biological process: rRNA processing
Cellular component: nucleolus; nucleoplasm; cytoplasm
Genetic constraint (gnomAD): Loss-of-function variants: 34 observed, 35.56 expected, observed/expected ratio (o/e) 0.96, 90% interval 0.73 to 1.27. The upper end of that interval is the gene's LOEUF score, 1.27, which puts it in group 5 of 6, group 1 being the genes least tolerant of losing a copy. Missense variants: 436 observed, 514.63 expected, observed/expected ratio (o/e) 0.85, 90% interval 0.78 to 0.92. Synonymous variants: 164 observed, 197.35 expected, observed/expected ratio (o/e) 0.83, 90% interval 0.73 to 0.95.
Homologues: Orthologues: chimpanzee WDR55 (99% identical), macaque WDR55 (97% identical), rabbit WDR55 (93% identical), dog WDR55 (92% identical), guinea pig WDR55 (92% identical), pig WDR55 (91% identical), rat Ik (89% identical), mouse Wdr55 (89% identical), tropical clawed frog ik (64% identical), zebrafish wdr55 (61% identical), Drosophila melanogaster CG14722 (33% identical), Caenorhabditis elegans Y44F5A.1 (24% identical). Paralogues in human: CSTF1 (21% identical), IK (11% identical).
Diseases named in the same sentence as WDR55 in open-access papers:
WDR55 is named in the same sentence as 5 diseases in open-access papers, as found by Europe PMC text mining. Sharing a sentence is not in itself a finding about the gene and the disease. The quoted sentences say what the papers report.
Alzheimer disease (1 paper, 2024). A progressive, neurodegenerative disease characterized by loss of function and death of nerve cells in several areas of the brain leading to loss of cognitive function such as memory and language. "Many of these genes have been previously linked to brain-related disorders, including Alzheimer’s disease (WDR12, AGFG2, and CDK5RAP3), schizophrenia (SRA1, WDR55, CORO7, DDAH2, PCDHA8), autism spectrum disorder (MAPK3, PCDHA13), and major depressive disorder (ZMAT2 and ITIH4)." (PMID 39269986, 2024).
WDR55 also shares sentences with these, for which no sentence is quoted: autism spectrum disorder (1 paper); liver cancer (1); major depressive disorder (1); schizophrenia (1).